TNF (tumor necrosis factor)
Diseases named in the same sentence as TNF in open-access papers (continued):
Sharing a sentence is not in itself a finding about the gene and the disease.
lung disease (continued). "The interaction between AAT and tumour necrosis factor alpha (TNF-alpha) was the subject of many studies, especially in patients with the AATD-associated lung disease." (PMID 34638908, 2021). "The KEGG pathway results demonstrated that the main pathways included IL-17 signaling pathway, AGE-RAGE signaling pathway in diabetic complications, TNF signaling pathway, pertussis, proteoglycans in cancer, and other contagious pulmonary diseases." (PMID 34088885, 2021). "We did not observe significant differences between the three sub-groups, although TNF-α levels were lower (with a borderline statistical significance) in the sub-group of patients with severe lung disease compared to moderate." (PMID 32326546, 2020). "These preliminary results suggest that salivary IL-6 and IL-8 levels increase during the acute phase of sinonasal disease (i.e., NTH), while the end stages of pulmonary disease and sinonasal disease (i.e., NP) show decreased TNF-α levels." (PMID 32326546, 2020). "A study revealed a significantly lower TNF-α with pulmonary disease while another study had higher TNF-α levels in pulmonary disease." (PMID 32264832, 2020). "Specifically, our results suggest that salivary IL-6 and IL-8 levels increase during the acute phase of sinonasal disease (i.e., NTH), while the end stages of pulmonary disease and sinonasal disease (i.e., NP) show decreased TNF-α levels." (PMID 32326546, 2020). "NF-κB is required for the transcription of many inflammatory genes involved in lung diseases, including interleukin-1β (IL-1β), IL-6, and tumor necrosis factor α (TNFα)." (PMID 32047419, 2020). "Our results show that both SAHA and TSA significantly inhibits (p < 0.05) TNFα-induced NFκB and IL-8 reporter activities, suggesting that HDACi has the potential to control TNFα-induced inflammation and/or chronic CF-lung disease." (PMID 29301535, 2018). "Apart from neutrophils, the other innate and adaptive immune cells also contribute to the pathophysiology of CF-lung disease by elevating levels of several pro-inflammatory cytokines and chemokines such as IL-1β, IL-6, IL-8, TNFα, IL-33 and IL-17." (PMID 29301535, 2018). "Many studies had revealed that the proinflammatory factory like TNF-a, IL-1a and IL-6 have an effect on the lung disease." (PMID 28521806, 2017). "Lung disease is known to sporadically occur after long-term use of 5-aminosalicylic acid and anti-tumor necrosis factor (TNF)-α antibodies." (PMID 27413560, 2016). "These mice also develop lung inflammation since overexpression of TNF-α in the lung induces a severe lung disease with alveolitis, fibrosis, emphysematous changes, endothelial changes, and platelet trapping." (PMID 27450561, 2016). "Many pulmonary diseases feature significant upregulation of cytokines such as tumor necrosis factor (TNF)-α." (PMID 27378943, 2016). "Nevertheless, other studies have reported associations between a number of cytokines, such as TNF-α, IL-1β, IL-6, IL17 and TGF-β1, and radiographic TB lung disease presentation." (PMID 27494953, 2016). "Cytokines such as TNF-alpha, IL-6, and IL-10, modulate the recruitment and the activation of leukocytes in lung diseases." (PMID 26569396, 2015). "The pre-treatment levels of IFN-γ and IL-12 were significantly lower in patients with MABC lung disease than control subjects, whereas the pre-treatment levels of TNF-α were upregulated in patients." (PMID 25295870, 2014). "The present study revealed that IL-8, IL-10, IL-18, TNF-α, and IP-10 are significantly correlated with pulmonary disease activity and global disease activity." (PMID 24800252, 2014). "Our results, showing the role of IL-1β in modifying TNF-α-induced pulmonary inflammation, are in support of a consideration for IL-1β neutralization in treatment of acute, and potentially chronic, TNF-α mediated lung diseases." (PMID 19901996, 2009).
lung disease (continued). "In P. brasiliensis-infected C57BL/6 mice, IL-4 neutralization leads to less severe pulmonary disease, low production of Th2 cytokines, high TNF-α and IL-12 synthesis, and low IgG1 antibodies levels." (PMID 19229338, 2009). "These in vitro and in vivo studies indicate that high level generation of TNFα leads to the exacerbation of inflammatory and prooxidative responses that are important in the pathogenesis of many diseases, including various pulmonary disorders." (PMID 17034639, 2006). "It is well demonstrated that pro-inflammatory cytokines such as TNF-α are involved in the pathogenesis of silica-induced lung disease." (PMID 16212659, 2005). "In many pulmonary diseases, TNF‐α generation leads to the development of inflammatory responses." (PMID 39172009, 2024). "IL-2 (p=0.02) and IFN-γ (p=0.001), but not TNF (p=0.79), were positively associated with cavitary lung disease regardless of CAC status." (PMID 39606489, 2024). "Biologic DMARDs with targets other than TNF-alpha appear to be associated with slower rate of progression of lung disease, whereas anti-TNF therapy does not correlate with a risk of ILD worsening." (PMID 37007765, 2023). "The TNF-α gene dysregulation is often associated with a high-level inflammatory process in many conditions other than COVID-19, such as CVD, atherosclerosis, and high susceptibility to lung disease risk." (PMID 36428884, 2022). "Our group found that non-anti-TNF bDMARDs were associated with poorer short-term progression of lung disease in a prospective cohort of 70 patients with RA-ILD." (PMID 33672699, 2021). "A decreasing trend of TNF-α in patients with severe lung disease was also observed." (PMID 32326546, 2020). "Therefore, uncovering the signaling components in TNF-α-mediated cPLA2 expression in HPAEpiCs is important to develop new therapeutic strategies in pulmonary diseases." (PMID 27932980, 2016). "Likewise, the development of NTM-related lung disease shortly after TNF antagonist treatment has provided further evidence for the possibility of latent MAC infection." (PMID 26406237, 2015). "In those cases, the use of the TNF-α blocking agents may trigger the onset of PM/DM or antisynthetase syndrome or may aggravate/trigger the lung disease." (PMID 24600322, 2014). "In those cases the use of the TNF-α blocking agents may trigger the onset of PM, DM, and antisynthetase syndrome or may aggravate or trigger the lung disease." (PMID 24600322, 2014). "Therefore, increased TNF-α in patients with MABC lung disease is more likely produced by Th17 cells than Th1 cells." (PMID 25295870, 2014). "Furthermore, higher ESR, CRP, and TNF-α titers, the occurrence of RA vasculitis, and RA lung disease emerged as strong disease-specific predictors of cardiovascular mortality." (PMID 23209899, 2012). "For example, epidemiologic features of patients who use anti–TNF-α drugs are similar to those who are at risk for NTM pulmonary disease in the absence of these drugs (i.e., elderly women, many of whom who have underlying lung disease)." (PMID 19861045, 2009). "This review very precisely describes the roles of TNFα in various pulmonary diseases." (PMID 17034639, 2006). "Despite some immunological side effects, anti-TNFα therapeutic strategies represent an important breakthrough in the treatment of inflammatory diseases and may have a role in pulmonary diseases characterized by inflammation and cell death." (PMID 17034639, 2006). "The following section discusses the role of TNFα in various pulmonary diseases." (PMID 17034639, 2006). "Anti-TNFα therapy for various pulmonary diseases overall has shown various levels of success." (PMID 17034639, 2006). "However, no conclusive data has yet been identified to prove the efficacy of anti-TNFα therapy for major pulmonary diseases." (PMID 17034639, 2006). "In addition, we found a decreasing trend of TNF-α in patients with severe lung disease." (PMID 32326546, 2020).
lung disease (continued). "Thus, the HO-1/CO system might suppress TNF-α-mediated inflammatory responses and exert a potential therapeutic strategy in pulmonary diseases." (PMID 30934992, 2019). "Also in African-American patients, severe pulmonary disease was associated with use of anti-TNF-α agents, and there was a non-significant trend toward association with male sex (P = 0.06)." (PMID 22195005, 2011). "All of these cytokines, TNF‐α, IL‐10, and IFN‐γ, are targets for treating different pulmonary diseases; for example, administration of recombinant human IFN‐γ results in favorable respiratory outcomes in patients exposed to sulfur mustard." (PMID 40330764, 2025). "Some other proteins such as TNF and POLE connected with different drugs that are used as anticancer agents and used to treat pulmonary diseases and hematologic malignancy." (PMID 40997149, 2025). "Numerous client proteins of Hsp90 have been identified in known cardiac and lung disease pathways, including MAPK signaling, PI3K/AKT (PKB)/mTOR, and TNF-α signaling." (PMID 38164161, 2024). "IL-6, TNF-α, IL-1β, and MIP-2 are representative pro-inflammatory cytokines and chemokines that are related to the pathogenesis of various lung diseases." (PMID 35326218, 2022). "Herein, we identify specific cytokines, such as IP-10, IL-18, TNF-α, and ISG54, that are elevated in hMPV mediated lung disease." (PMID 27171557, 2016). "In the pathogenesis of bleomycin-induced lung disease, transforming growth factor-β (TGF-β), tumor necrosis factor-α (TNF-α), IL-1, IL-5, IL-6, platelet-derived growth factor (PDGF) and a variety of cytokines such as chemokines play important roles." (PMID 23558450, 2013). "In addition, tumor necrosis factor-alpha (TNF alpha) and interleukin-6 (IL-6) affected the progression of lung diseases." (PMID 40242447, 2025). "Consequently, TNF release via necroptosis activation creates a positive feedback loop, exacerbating RSV-induced lung disease." (PMID 40371107, 2025). "More recently, animals infected with NML-33 and NML-37 strains also develop a strong pulmonary disease in absence of TNF-α secretion." (PMID 35437094, 2022). "Up to date, it has been shown that in pulmonary diseases marked by inflammatory features, a typical raise in serum CRP level takes place in response to inflammatory cytokines such as interleukin (IL)-6, IL-1 or tumoral necrosis factor (TNF)-α." (PMID 35809152, 2022). "A large number of biomarkers with the potential to detect lung disease were investigated in the literature summarised in this review, including (but not limited to): Club/Clara cell protein 16 (CC16); serum HO-1; IL6; TNFα, IL6, and IL8; and Npnt." (PMID 34360414, 2021). "Neutralization of pro-inflammatory cytokines such as IL-6, TNF-α, VEGF, and IFN-α/β, as well as anti-inflammatory IL-4, during severe pulmonary disease may help reduce ongoing parenchymal damage in the MTB-infected lung." (PMID 28125719, 2017). "IL-1β may enhance TNF-α-induced neutrophil recruitment to the lung by altering TNF receptors as well as MIP-2 and KC production in pulmonary diseases." (PMID 24696530, 2014). "Peripheral blood mononuclear cells (PBMCs) from NTM patients were shown to produce less Th1 cytokines (IFN-γ, IL-12, and TNF-α) compared to healthy controls, suggesting that NTM lung disease might reflect defects in the IL-12/IFN-γ pathway." (PMID 25295870, 2014). "TNF-α is a upstream regulatory factor of this process, which can induce accumulation of macrophages, secrete large amount of TGF-β and ET-1, expand the inflammatory response, and promote the formation of synovitis inflammation and lung disease." (PMID 23365580, 2012). "We compared the effects of a protective versus a conventional ventilatory strategy, on systemic and lung production of tumor necrosis factor-α (TNF-α) and interleukin-8 (IL-8) in patients without lung disease." (PMID 20236550, 2010).
lung disease (continued). "In contrast to the experimental studies several recent clinical trials showed either very little or no beneficial effect during anti-TNFα therapy in pulmonary diseases." (PMID 17034639, 2006). "We do not know whether these biologics have an intrinsic effect on RA-ILD, although studies published in the last few years point to the stabilization of lung disease with non-anti-TNF bDMARDs." (PMID 33672699, 2021). "Thus, our finding of significant increases in Blue area (cells) without changes in Pink area confirm previous reports that TNF driven lung disease comprises a largely lymphocytic disease process, but in our model, does not progress to a fibrosing disease." (PMID 29320550, 2018). "Recently, treatment with recombinant TNF-α in the presence of IFN-γ was found to enhance mycobacterial killing, whereas defects in TNF-α or its receptor were found to promote M. tuberculosis replication and progressive lung disease in M. tuberculosis-infected mice." (PMID 27148227, 2016). "Thus TNF-α-driven lung disease is not sufficient to induce inflammatory arthritis in mice." (PMID 27450561, 2016). "Plasma levels of IL-6, tumor necrosis factor, IL-10, and IL-1 receptor antagonist remained low after 1 h of IMV in 39 adults with no previous lung disease." (PMID 35844745, 2022). "For the first time, IP-10 (in contrast to IFN-γ, TNF-α, IL-2, IL-8, MIP-1α, MIP-1β and RANTES) has been detected in the urine of patients with lung disease in the absence of renal illnesses." (PMID 21092156, 2010). "The major finding of the study is that both TNF-α and IL-8 concentrations were increased with high VT but stable with low VT in the BAL fluid in patients ventilated without lung disease after admission to an ICU." (PMID 20236550, 2010). "IP-10, in contrast to IFN-γ, TNF-α, IL-2, IL-8, MIP-1α, MIP-1β and RANTES, is detectable in the urine of patients with pulmonary diseases in the absence of renal dysfunctions." (PMID 21092156, 2010). "Furthermore, serum levels of IL-10 significantly increased while TNF-and ESR values substantially decreased from day 0 to day 60 of ATT in patients with cavitary TB but not in those with non-cavitary lung disease." (PMID 27494953, 2016). "However, this therapeutic benefit of TNF-armed MYXV/PBMC therapy, with or without ICI co-therapy, is lost In the later stage advanced disease model (defined as treatment beginning only after a lung disease burden of 5 × 106 luminescence units is achieved)." (PMID 35053501, 2022). "The excessive uncontrolled inflammatory responses mainly led by IL-6, IFNγ, TNFα, CRP, D-dimer, VES, and the lack of vitamin D (pre-hormone D) were common clinical traits of this infection, though those parameters were common to other types of lung diseases and infections." (PMID 36428884, 2022). "Finally, about the fact that pulmonary disease was unaffected by IFN-K, we think that a non-IFN-dependent pathologic process might be mediating lung damage, as it has previously been improved in MRL/lpr mice by inhibiting Tumor Necrosis Factor-α." (PMID 34867938, 2021).
non-alcoholic fatty liver disease (150 papers, 2011 to 2025). "Accordingly, an abundant expression of pro-inflammatory cytokines IL-1β and TNF-α is often associated with Non-Alcoholic Fatty Liver Disease (NAFLD)." (PMID 31935892, 2020). "Further, P. gingivalis decreased insulin sensitivity and increased pro-inflammatory cytokines TNF-α and IL-6, causing an inflammatory response in the liver by lipid droplet formation indicating that periodontitis may affect nonalcoholic fatty liver disease (NAFLD;)." (PMID 33504065, 2021). "Results of several animal and human studies suggest that intestinal bacteria overgrowth may be involved in pathologies, including non-alcoholic fatty liver disease, and increases in LPS binding protein that are associated with a marked increase expression of TNF-α." (PMID 28420148, 2017). "The flavonoid hesperidin significantly enhances GLP-1 secretion and reduces pro-inflammatory biomarkers such as IL-6, TNF-α, and hsCRP in both clinical and preclinical models of non-alcoholic fatty liver disease." (PMID 40904779, 2025). "Another study reported that NS supplementation led to a reduction in TNF-α levels in patients with non-alcoholic fatty liver disease." (PMID 40076857, 2025). "In another study, it was reported that the relative abundance of Lachnoclostridium contributed to dysbiosis and was positively correlated with IL‐6, TNF‐α and cholesterol levels in mice with a high‐fat diet and nonalcoholic fatty liver disease model." (PMID 39620016, 2024). "It decreased TNF-α, a key factor in Non Alcoholic Fatty Liver Disease (NAFLD) and Non Alcoholic Steato Hepatitis (NASH) development, as well as IL-6, IL-10, and IL-17A, which are implicated in obesity and NAFLD regulation." (PMID 38611444, 2024). "In non-alcoholic fatty liver disease, SalB reduces the expression levels of NF-κB p65, IL-6, and TNF-α in the liver, mitigating liver damage." (PMID 39459158, 2024). "It is well known that high TNFα and VEGF levels have been linked to an increased risk of liver-related dysfunction, such as nonalcoholic fatty liver diseases, liver cirrhosis, apoptosis, etc.." (PMID 37892137, 2023). "TNF-α secreted from the macrophages can result in the death of hepatocytes, which is involved in nonalcoholic fatty liver disease (NAFLD)." (PMID 38139082, 2023). "There are 138 potential gene targets of S. chinensis for the treatment of ALD, and the pathways involved PI3K-Akt signaling pathway, TNF signaling pathway, non-alcoholic fatty liver disease, and nuclear factor kappa-B (NF-κB) signaling pathway." (PMID 35252302, 2022). "Markers of liver inflammation such as interleukin-6 (IL-6) and tumor necrosis factor alpha (TNFα), which are important in the progression of non-alcoholic fatty liver disease to non-alcoholic steatohepatitis were decreased by NCT." (PMID 35087037, 2022). "Acupuncture at ST36, CV4, and KI1 was reported to reduce inflammatory factors, such as TNF-α, and inflammatory cell infiltration in a nonalcoholic fatty liver disease model." (PMID 35928244, 2022). "The enriched KEGG pathways involved in c-Fos mainly contained MAPK signaling pathway, PI3K-Akt signaling pathway, TNF signaling pathway, non-alcoholic fatty liver disease, C-type lectin receptor signaling pathway and IL-17 signaling pathway." (PMID 35641944, 2022). "Mice exposed to PM2.5 has been demonstrated to have increased mRNA expressions of inflammatory cytokines such as TNFα, IL-6 and exhibited Non-alcoholic fatty liver disease (NAFLD)." (PMID 33953864, 2021). "Other proinflammatory cytokines like tumor necrosis factor α (TNFα) and interleukin 1β (IL1β) increased as the nonalcoholic fatty liver disease progressed." (PMID 34597305, 2021). "Synchronously, ARRB1 also mediated the development of nonalcoholic fatty liver disease through TRAFs, which is another important member of TNF-α pathway." (PMID 33753990, 2021).